USP18 (ubiquitin specific peptidase 18)
Diseases named in the same sentence as USP18 in open-access papers (continued):
Sharing a sentence is not in itself a finding about the gene and the disease.
pancreatic cancer (continued). "Next, using Western blot, we measured the protein levels of c-Myc in 30 pancreatic cancer tissues with high USP18 expression." (PMID 33051403, 2020). "Overall, these results suggested that USP18 promotes pancreatic cancer cell proliferation by facilitating cell cycle progression and inhibiting cell apoptosis." (PMID 33051403, 2020). "Multivariate Cox regression analysis further revealed that high USP18 expression was an independent predictor of poor survival in patients with pancreatic cancer." (PMID 33051403, 2020). "Overall, these results demonstrated that USP18 contributes to the progression of pancreatic cancer and is dependent on the Notch1/c-Myc signalling pathway." (PMID 33051403, 2020). "Confocal microscopy was used to further confirm the co-localization of USP18 and Notch1 in pancreatic cancer cells, which provided further evidence of an interaction between these two proteins." (PMID 33051403, 2020). "Moreover, flow cytometry showed that downregulation of USP18 significantly arrested the cell cycle in G1 phase in pancreatic cancer cells." (PMID 33051403, 2020). "Importantly, in this study, our results demonstrated for the first time that USP18-mediated regulation of c-Myc-induced pancreatic cancer cell progression is dependent on Notch1." (PMID 33051403, 2020). "Moreover, USP18 expression was analysed in 108 pancreatic cancer tissue samples and was compared with the expression in adjacent nontumour tissues by immunohistochemical staining." (PMID 33051403, 2020). "Furthermore, scatter plots showed that the USP18 and c-Myc mRNA expression levels were positively correlated in pancreatic cancer tissues." (PMID 33051403, 2020). "Furthermore, we found that the expression of USP18 was significantly upregulated in pancreatic cancer tissues compared with adjacent normal tissues." (PMID 33051403, 2020). "Additionally, to further explore the efficiency of USP18 in the survival of pancreatic cancer patients, high USP18 expression in pancreatic cancer patients was correlated with poor Overall Survival and Disease-Free Survival." (PMID 33051403, 2020). "To test this hypothesis, we first observed whether USP18 and Notch1 directly interact in pancreatic cancer cells, and interestingly, co-IP demonstrated an interaction between USP18 and Notch1." (PMID 33051403, 2020). "Therefore, we analysed the TCGA database to further evaluate the expression of USP18 in pancreatic cancer." (PMID 33051403, 2020). "Importantly, we also measured the protein levels of Notch1 in 30 pancreatic cancer tissues with high USP18 expression." (PMID 33051403, 2020). "In addition, our results showed that the percentage of apoptotic cells was significantly increased in the USP18 knockdown pancreatic cancer cells." (PMID 33051403, 2020). "Second, c-Myc is crucial for USP18-mediated pancreatic cancer progression." (PMID 33051403, 2020). "Collectively, these results suggested that USP18 may play a role in pancreatic cancer development and progression." (PMID 33051403, 2020). "Conversely, these phenomena were reversed after USP18 was silenced in pancreatic cancer cells." (PMID 33051403, 2020). "To further determine whether USP18 could regulate c-Myc expression, we first measured the protein and mRNA levels of c-Myc in USP18-knockdown pancreatic cancer cells." (PMID 33051403, 2020). "First, USP18 and Notch1 directly interact in pancreatic cancer cells." (PMID 33051403, 2020). "Further investigation revealed that USP18 promoted cell progression by increasing c-Myc expression, which has been reported to control pancreatic cancer progression, and our data demonstrated that c-Myc is key for USP18-mediated pancreatic cancer cell progression in vitro and in vivo." (PMID 33051403, 2020). "To further clarify the mechanism through which USP18 regulates c-Myc in pancreatic cancer cells, we first determined whether there was a direct interaction between the USP18 and c-Myc proteins." (PMID 33051403, 2020).
pancreatic cancer (continued). "Furthermore, we detected the effects of USP18 on pancreatic cancer cell proliferation by CCK8 and EdU assay." (PMID 33051403, 2020). "Moreover, we found that USP18 promoted pancreatic cancer progression via upregulation of Notch-1-dependent c-Myc." (PMID 33051403, 2020). "Therefore, all these studies suggested that USP18 may represent a novel indicator of poor prognosis in pancreatic cancer and may function as an oncogene in pancreatic cancer progression." (PMID 33051403, 2020). "However, the role of deubiquitinase ubiquitin-specific protease 18 (USP18) in pancreatic cancer remains unknown." (PMID 33051403, 2020). "In conclusion, these findings may provide novel insight into the cancer-promoting effects of USP18 and its potential clinical application in pancreatic cancer, which suggests that the USP18/Notch1/c-Myc pathway may act as a crucial regulator of pancreatic cancer progression." (PMID 33051403, 2020). "Finally, we explored the effect of USP18 on cell signalling pathways in pancreatic cancer cells." (PMID 33051403, 2020). "The quantitative scoring showed that USP18 protein was expressed at significantly higher levels in pancreatic cancer tissues compared with adjacent nontumour tissues." (PMID 33051403, 2020). "The results showed that USP18 protein was upregulated in pancreatic cancer tissues compared with adjacent nontumour tissues." (PMID 33051403, 2020). "QRT-PCR revealed that the average fold change of USP18 mRNA expression in pancreatic cancer tissues compared with adjacent nontumor tissues." (PMID 33051403, 2020).
parasitemia (1 paper, 2016). "C57BL/6 mice infected with N67 parasite induced a strong IFN-I response, including increased expression of genes such as Cd40, Isg15, Isg20, Ifit2, Mx1, Mx2, Ddx58, and Usp18 genes, leading to suppression of N67 parasitemia." (PMID 27716849, 2016).
pericardial effusion (1 paper, 2022). Fluid collection within the pericardial sac, usually due to inflammation. "The expression levels of USP18 and IFI44 were likewise lower in the serositis positive group, which included SLE patients with pleural effusion or pericardial effusion, than in SLE patients without serositis." (PMID 35967341, 2022).
polymicrogyria (1 paper, 2021). A developmental brain abnormality characterized by an excessive amount of small convolutions on the surface of the brain and cognitive dysfunction. "Recently, a set of loss of function recessive mutations in ubiquitin-specific peptidase 18 (USP18), a key negative regulator of type I interferon response, have been associated grossly with brain calcification and polymicrogyria." (PMID 33498715, 2021).
prediabetes (1 paper, 2023). "The reduced expression of USP18, a DUB involved in regulating inflammation, was observed in diabetic mice, suggesting impaired UPS regulation in the early prediabetes stages." (PMID 37895057, 2023).
pseudo-TORCH syndrome (1 paper, 2025). "The importance of this scaffolding function of USP18 is illustrated by human patients harboring USP18 mutations, which give rise to interferonopathies, such as pseudo-TORCH syndrome, whose characteristic is the loss of interferon signaling." (PMID 40436319, 2025).
pulmonary fibrosis (1 paper, 2023). Chronic progressive interstitial lung disorder characterized by the replacement of the lung tissue by connective tissue, leading to progressive dyspnea, respiratory failure, or right heart failure. "To bolster our understanding of Foxo3 and Usp18 in the context of pulmonary fibrosis, we scoured the GEO database." (PMID 38025194, 2023). "Harnessing the abundance of publicly accessible data resources, we embarked on an exhaustive examination of the roles and implications of FOXO3a and USP18 in pulmonary fibrosis." (PMID 38025194, 2023).
relapsing-remitting MS (1 paper, 2024). "Low levels of USP18 mRNA were detected in the peripheral blood mononuclear cells of patients with relapsing-remitting MS (RRMS), which could possibly lead to enhanced TNF and type-I interferon (IFN) signaling as these DUBs are major negative regulators of immune signaling." (PMID 38716888, 2024).
serous ovarian cancer (1 paper, 2024). "In our study, we have shown that ISG15, ISGylation and USP18 are increased in ascites cells when compared with normal ovarian surface epithelial cells and less aggressive high grade serous ovarian cancer cells." (PMID 38939897, 2024).
ZIKV infection (1 paper, 2017). "ZIKV induction of the ISG15 family further suggests the potential for USP18-directed downregulation of IFN-α/β translation and for HERC5 to enhance IRF stability that may drive ISG induction during ZIKV infection." (PMID 28698279, 2017).
infection (60 papers, 2009 to 2025). The state of being infected such as from the introduction of a foreign agent such as serum, vaccine, antigenic substance or organism. "Nevertheless, differences were observed in USP18-deficient animals that were infected with different viruses via different infection routes." (PMID 37978268, 2023). "In this model, liver inflammation leads to increased hepatocyte USP18, which in turn makes the liver more susceptible to infections targeting the hepatocyte, such as HCV." (PMID 27009955, 2016). "One possibility is that USP18 increases the susceptibility of the cell to infection by HCV." (PMID 31871427, 2019). "We speculate that by blocking IFN-α signaling, USP18 expression may lead to an enhanced susceptibility to infection with interferon-sensitive viruses and enhanced viral proliferation." (PMID 27009955, 2016). "For example, expression of genes encoding for DDX58/RIG-I, USP18, SAMHD1, and several members within the IFIT family was greater in response to SARS-CoV-2 than SARS-CoV-1 infection." (PMID 39874350, 2025). "Previous studies have primarily focused on elucidating the regulatory function of USP18 in antiviral and antibacterial infection responses by inhibiting the type I interferon (IFN) signaling pathway independently of its catalytic activity." (PMID 40514377, 2025). "A set of upregulated in vitro and in vivo genes following infection were also strongly confined to Cluster 1 including Usp18, Tmem17 involved with tumor progression, and antiviral gene Ddx60." (PMID 40523037, 2025). "We predicted that the elevated expression of ISGs in USP18.I60N‐expressing cells would engender resistance to infection." (PMID 39931755, 2025). "USP18 regulates the antiviral and antibacterial infection responses by inhibiting the IFN signaling pathway independently of its catalytic activity." (PMID 40514377, 2025). "Intriguingly, genes such as Ifi204, Irgm1/2, Nos2, Gbp3/7, Usp18, Irf7, Stat1, and Isg15, which were upregulated in response to infection in cells treated with siR_Ctrl, showed decreased upregulation in cells treated with siR_Nostrill following infection." (PMID 39040107, 2024). "IFI6 was reported to block flavivirus replication, and USP18 was reported to counteract infection by Sendai virus and encephalomyocarditis virus." (PMID 37306574, 2023). "The upregulation of ISG15, ISG20, ISG15 family ligases (HERC5/6), and ISG15 proteases (USP18) also appeared upon infection, which has been reported to participate in host antiviral immunity." (PMID 37752509, 2023). "Infection of Usp18−/− peritoneal macrophages with EMCV also led to a decrease in fold change of Ifnb and its downstream Ccl5 gene mRNA levels as well as the production of IFN-β compared with the WT counterparts." (PMID 34016972, 2021). "In summary, we have identified a deubiquitinase USP18 as a host factor modulating MAVS aggregation during the infection of RNA viruses." (PMID 34016972, 2021). "USP18 upregulates the expression and production of type I interferon following infection with Sendai virus (SeV) or Encephalomyocarditis virus (EMCV)." (PMID 34016972, 2021). "We found, by ELISA analysis, that the production of IFN-β in the serum of Usp18−/− mice was significantly lower than that of Usp18+/+ mice after infection with VSV." (PMID 34016972, 2021). "Consistent with the observation from the siRNA knockdown of USP18, infection of Usp18−/− macrophages with SeV led to a decrease in fold changes of Ifnb mRNA as well as the production of IFN-β compared with Usp18+/+ macrophages." (PMID 34016972, 2021). "In the present study, we highlighted the distinct role of Usp18 in CD169+ macrophages during natural infection and its potential role during vaccination." (PMID 32210083, 2020). "In these cells, mouse IFN-αA and IFN-λ3 treatments significantly up-regulated the expression of the IFN-stimulated genes (ISGs) Oasl2 and Usp18, and significantly decreased infection by TM967, a TMEV derivative expressing mCherry." (PMID 31426334, 2019).
infection (continued). "Considering that the SAMHD1KO cells exhibited significantly low p21 mRNA and to avoid the pleotropic effect of viral protein VPX in our infection assays, we explored further the mechanism of USP18-mediated downregulation of p21 in the SAMHD1KO THP-1 cells." (PMID 31455647, 2019). "In contrast to IFN-λ treatment, IFN-α treatment of this clone failed to induce the expression of the IFN-stimulated genes, Oasl2 and Usp18, and to protect against infection with TM967, a TMEV derivative expressing mCherry." (PMID 30335553, 2018). "This suggests a role of USP18 in positively regulating expression of type I IFNs and proinflammatory cytokines after infection with a DNA virus." (PMID 30126853, 2018). "Similarly, there were increases in abundance after death of genes that are required for innate (Laao, Tox2) and adaptive immunity (Ms4a17, Usp18) and increased levels of the apoptotic genes (Fosb, Bcl2l11) that are normally activated by infection and injury." (PMID 36982814, 2023). "Furthermore, Usp18−/− mice were less resistant to infection with VSV compared with Usp18+/+ mice through intraperitoneal injection, exhibiting significantly reduced survival time." (PMID 34016972, 2021). "Furthermore, hematoxylin-and-eosin staining showed greater infiltration of immune cells and injury in the lungs of Usp18−/− mice, relative to that in the lungs of Usp18+/+ mice, after infection with VSV." (PMID 34016972, 2021). "Accordingly, USP18 might be a good candidate for developing therapeutic agents to control DENV and potentially other viruses’ infections, although the USP18-mediated antiviral mechanism needs to be further investigated." (PMID 34017322, 2021). "Indeed, during subcutaneous infection, the presence of Usp18 in CD169 MΦs was also essential for early replication." (PMID 32210083, 2020). "To investigate whether the route of infection influenced the importance of Usp18 in CD169+ macrophages, we infected WT and CD169-Cre+/ki x Usp18fl/fl mice subcutaneously with VSV and analyzed the viral replication in dLN after 16 h." (PMID 32210083, 2020). "In line, CD169-Cre+/ki x Usp18fl/fl mice showed reduced innate and adaptive immune responses against the VSV wildtype strain and died quickly after infection, suggesting that a lack of Usp18 makes mice more susceptible to the side effects of the VSV vector." (PMID 32210083, 2020). "Consequently, for the proteomics analysis, we infected Isg15−/−, wild-type, and USP18 C61A/C61A mice via intravenous injection and harvested liver tissue following 72 h of infection." (PMID 31772204, 2019). "USP18-deficient mice (Sv129 × C57BL/6 mixed background) that were treated with vesicular stomatitis virus (VSV) were reported to have increased viral replication in spinal cord and brain and die within 1 week whereas wild-type mice survive the infection." (PMID 30126853, 2018). "However, in the murine system when the ISGylation machinery is overexpressed prior to infection or when USP18-mutant cells are infected, where high levels of ISG15 conjugation are observed, viral titers decrease by more than one log." (PMID 29077752, 2017). "One could have predicted an even better rescue of both the ISG expression and infection phenotypes by ISG15ΔGG, since the latter should be more readily accessible to mediate USP18 stability than the conjugation-competent form of ISG15." (PMID 27193971, 2016). "Interestingly, our RT-qPCR data reveals that the meta-genes ATOX1, OAS2 and USP18 were consistently up-regulated with a distinct pattern with infection time-course in THP-1 cells infected with DENV-1 or DENV-2." (PMID 27651116, 2016). "The selected targets included genes that were differentially expressed in both gt1‐ and gt3‐infected samples versus controls (CXCL9, IFIT1, ISG15 and RSAD2), as well as genes that were differentially regulated only in gt1 infection (USP18) or gt3 infection (IDO1)." (PMID 25800823, 2015).